APOL6 (apolipoprotein L6)
Description:
May affect the movement of lipids in the cytoplasm or allow the binding of lipids to organelles.
Synonyms: ApoL-VI; APOLVI
Tractability: Antibody: its Gene Ontology location is reachable by antibodies, with medium confidence. PROTAC: ubiquitination databases record sites on it.
Gene: Protein-coding gene on chromosome 22 (35,648,386 to 35,668,404, forward strand). Ensembl gene ENSG00000221963.
Subcellular location: Cytoplasm
Subcellular location (Human Protein Atlas): Nuclear bodies; Nucleoplasm; Cytosol
Gene Ontology:
Molecular function: protein binding; lipid binding
Biological process: lipid transport; lipoprotein metabolic process
Cellular component: nuclear body; nucleoplasm; membrane; cytoplasm; extracellular region
Genetic constraint (gnomAD): Loss-of-function variants: 2 observed, 3.35 expected, observed/expected ratio (o/e) 0.6, 90% interval 0.24 to 1.66. That is too few expected variants to judge how well the gene tolerates losing a copy. Missense variants: 438 observed, 450.76 expected, observed/expected ratio (o/e) 0.97, 90% interval 0.9 to 1.05. Synonymous variants: 189 observed, 178.8 expected, observed/expected ratio (o/e) 1.06, 90% interval 0.94 to 1.19.
Homologues: Orthologues: chimpanzee APOL6 (83% identical), macaque APOL6 (78% identical), dog APOL6 (43% identical), mouse Apol6 (40% identical), zebrafish apol (20% identical), Caenorhabditis elegans F07F6.8 (10% identical), Caenorhabditis elegans F07F6.7 (9% identical). Paralogues in human: APOL5 (33% identical), APOL3 (31% identical), APOL1 (29% identical), APOL2 (29% identical), APOL4 (24% identical), APOLD1 (16% identical).
Diseases named in the same sentence as APOL6 in open-access papers:
APOL6 is named in the same sentence as 38 diseases in open-access papers, as found by Europe PMC text mining. Sharing a sentence is not in itself a finding about the gene and the disease. The quoted sentences say what the papers report.
colon cancer (3 papers, 2020 to 2023). "APOL6 showed a low expression level in colon cancer tissues and was a low-risk gene." (PMID 35991564, 2022). "It was due to the ability of APOL6 to induce apoptosis in colon cancer cells." (PMID 35991564, 2022). "ALPL, APOL6, SON, VWF, FITM2, and ZEB1-AS1 were significantly differentially expressed in normal and colon cancer tissues." (PMID 35991564, 2022). "Moreover, we transfected RKO colon cancer cells with APOL1-KO, APOL2-KO, APOL3-KO, APOL4-KO and APOL6-KO." (PMID 36923931, 2023).
colorectal cancer (3 papers, 2023 to 2025). A primary or metastatic malignant neoplasm that affects the colon or rectum. "APOL gene overexpression, especially APOL1 and APOL6, has been reported to promote apoptosis in embryonic kidney cells, podocytes and colorectal cancer cell lines." (PMID 37924378, 2024).
atherosclerosis (2 papers, 2023). A disease characterized by the build-up of fatty material and calcium deposition in the arterial wall resulting in partial or complete occlusion of the arterial lumen. "Furthermore, APOL6-induced cell apoptosis might be a potential therapeutic target for treating atherosclerosis and cardiovascular disease." (PMID 38017264, 2023).
diabetes (2 papers, 2024). "Considering the GWAS data of ApoL6 SNP association with triglyceride levels in humans, ApoL6 may provide a future therapeutic target against obesity/diabetes and FLD." (PMID 38167864, 2024). "Thus, ApoL6 ablation decreases white adipose tissue mass, protecting mice from diet-induced obesity, while ApoL6 overexpression in adipose brings obesity and insulin resistance, making ApoL6 a potential future target against obesity and diabetes." (PMID 38167864, 2024). "We observed a significantly higher protein expression of APOL1 by 12.8-fold in islets from three donors with (pre-)diabetes, while APOL2 and APOL6 were not significantly altered in these donors." (PMID 37924378, 2024).
glioma (2 papers, 2021 to 2024). A benign or malignant brain and spinal cord tumor that arises from glial cells (astrocytes, oligodendrocytes, ependymal cells).
melanoma (2 papers, 2023 to 2024). A malignant, usually aggressive tumor composed of atypical, neoplastic melanocytes. "The Kaplan–Meier survival curves showed that the upregulation of APOL6 was associated with prolonged survival in melanoma (p values < 0.001) and urothelial cancer (p values < 0.05)." (PMID 36979348, 2023). "According to the previous analysis, the upregulation of APOL6 was an independent protective factor for improved response and prognosis in melanoma and urothelial cancer (including BLCA)." (PMID 36979348, 2023). "Moreover, the clinical significance of APOL6 was only evaluated in melanoma, urothelial cancer and breast cancer cohorts." (PMID 36979348, 2023). "As a regulator of lipid metabolism, APOL6 affected metabolic processes such as regulation of intestinal lipid absorption (GO: 1904729), positive regulation of fatty acid transport (GO: 2000193) and lipid binding (GO: 0008289) in melanoma." (PMID 36979348, 2023).
pancreatic cancer (2 papers, 2023). "Bioinformatic analyses predicted that upregulation of APOL6 may cause multiple forms of cell death in pancreatic cancer." (PMID 36979348, 2023). "Pancreatic cancer cells transfected with APOL6 overexpression plasmid underwent apoptosis, necroptosis, and pyroptosis with immunogenic features." (PMID 36979348, 2023). "As expected, our data confirmed that the upregulation of APOL6 promoted necroptosis and pyroptosis in pancreatic cancer." (PMID 36979348, 2023). "In vitro experiments found that up-regulation of APOL6 could promote the necrosis and pyroptosis of pancreatic cancer cells, while necrosis and pyroptosis could enhance anti-tumor immune effects, which also indirectly explained the up-regulation of APOL6 in immunotherapy responders." (PMID 38012642, 2023).
Cirrhosis (1 paper, 2023). A chronic disorder of the liver in which liver tissue becomes scarred and is partially replaced by regenerative nodules and fibrotic tissue resulting in loss of liver function. "For the GSE14520 cohort, nomograms were constructed using tumor size, cirrhosis, α-fetoprotein (AFP), Barcelona Clinic Liver Cancer (BCLC) stage, APOL3 and APOL6 expressions for OS." (PMID 38017264, 2023). "Nomograms were constructed using sex, cirrhosis, BCLC stage, APOL2, APOL3 and APOL6 expression for RFS." (PMID 38017264, 2023). "Small tumor size; female sex; lack of cirrhosis; BCLC stage 0; high expression of APOL2, APOL3 and APOL6; and low AFP levels indicated higher survival rate in the GSE14520 cohort." (PMID 38017264, 2023).
COVID-19 (1 paper, 2024). A disease caused by infection with severe acute respiratory syndrome coronavirus 2. "Both the RNA editing (APOL6:chr22:35660551, and APOL6:chr22:35660499) and gene expression levels of APOL6 significantly increased upon COVID-19 vaccines." (PMID 39308856, 2024). "One of the most significant DRE in RNA editing in response to COVID-19 vaccines was in apolipoprotein L6 (APOL6) 3’ UTR, which positively correlated with its up-regulated expression." (PMID 39308856, 2024).
gastric cancer (1 paper, 2025). A primary or metastatic malignant neoplasm involving the stomach. "KM analysis of clinical data revealed that high expression of APOL6 was associated with improved survival rates in patients with pancreatic, ovarian, lung, liver, and gastric cancers who underwent immunotherapy." (PMID 40141028, 2025).
Genetic obesity (1 paper, 2024). "ApoL6 expression is increased in WAT of HFD-induced and genetic obesity mouse models (Previous reported downregulation of ApoL6 during adipocyte differentiation and genetic obesity were not reproducible in our hands." (PMID 38167864, 2024).
hepatitis C virus infection (1 paper, 2021). A viral infection caused by the hepatitis C virus. "APOL2 was shown to inhibit Hepatitis C virus infection and APOL6 has been shown to inhibit poliovirus." (PMID 34252458, 2021).
Impaired glucose tolerance (1 paper, 2024). An abnormal resistance to glucose, i.e., a reduction in the ability to maintain glucose levels in the blood stream within normal limits following oral or intravenous administration of glucose. "Conversely, overexpression of ApoL6 in adipocytes leads to larger LD with high TAG content in adipocytes and in WAT of mice with greater WAT mass, making mice more susceptible to weight gain, resulting in impaired glucose tolerance, insulin resistance, and ectopic TAG accumulation in the liver." (PMID 38167864, 2024).
influenza (1 paper, 2025). An acute viral infection of the respiratory tract, occurring in isolated cases, in epidemics, or in pandemics; it is caused by serologically different strains of viruses (influenzaviruses) designated A, B, and C, has a 3-day incubation period, and usually lasts for 3 to 10 days. "Additionally, a signature associated with influenza (APOL6, IFIT3) was detected in the disease category." (PMID 40916026, 2025).
Insulin resistance (1 paper, 2024). Increased resistance towards insulin, that is, diminished effectiveness of insulin in reducing blood glucose levels. "Indeed, after 10 wks of HFD feeding, WT mice had high glucose levels and insulin resistance as expected, whereas ApoL6 KO mice had significantly lower glucose levels at 15, 30 and 60 min after glucose injection." (PMID 38167864, 2024).
Obesity (1 paper, 2024). Accumulation of substantial excess body fat. "Our global ApoL6 KO mice showed protection from diet-induced obesity, while mice overexpressing ApoL6 in adipose tissue showed exacerbated adiposity." (PMID 38167864, 2024). "WAT depot weights also were significantly reduced in ApoL6 KO mice compared to WT mice, suggesting that ApoL6 KO mice were prevented from HFD-induced obesity." (PMID 38167864, 2024). "Thus, ApoL6 knockdown or ablation results in smaller LD with lower TAG content in adipocytes and in WAT of mice that become resistant to diet-induced obesity." (PMID 38167864, 2024).
osteoarthritis (1 paper, 2023). A noninflammatory degenerative joint disease occurring chiefly in older persons, characterized by degeneration of the articular cartilage, hypertrophy of bone at the margins and changes in the synovial membrane. "Notably, the identified here interactions between hsa-let7b/i, hsa-miR-221/222-3p, hsa-miR-302c, hsa-miR-181a, hsa-miR-331 with target genes HMGA2, IGF2BP3, STARD4, and APOL6 could prove to be the necessary tools that will convey iMSCs into the ideal mean for cell therapy in osteoarthritis." (PMID 37443790, 2023).
rectal cancer (1 paper, 2023). A primary or metastatic malignant neoplasm that affects the rectum. "In summary, we identified five radiosensitivity-related genes associated with rectal cancer prognosis: TOP2A, MATR3, APOL6, JOSD1, HOXC6." (PMID 38012642, 2023). "In subsequent studies, we will perform cell function experiments, xenograft experiments in nude mice, and molecular mechanism experiments on irradiated human rectal cancer cell lines after overexpression or knockdown of TOP2A, MATR3, APOL6, JOSD1, and HOXC6." (PMID 38012642, 2023). "qRT-PCR revealed that MATR3 expression was different in rectal cancer tissues and adjacent non-cancerous tissues, while APOL6, HOXC6, JOSD1, and TOP2A expression was not different." (PMID 38012642, 2023). "Through the random survival forest analysis of these 1153 differential genes, we finally screened five key genes, which were the radiosensitivity up-regulated genes of rectal cancer: TOP2A, MATR3, APOL6, JOSD1 and the radiosensitivity down regulated gene of rectal cancer: HOXC6." (PMID 38012642, 2023). "We found that TOP2A, APOL6, MATR3 were correlated with MSI and could be used as potential indicators of sensitivity to immunotherapy for rectal cancer." (PMID 38012642, 2023).
viral infections (1 paper, 2021). "Two elements had differential expression for all 4 viral infections — MER4_22q12.3 and L1FLnI_7q21.2o — which intersect with the human genes APOL6 and SAMD9, respectively." (PMID 34731091, 2021).
tumor (10 papers, 2019 to 2024). "EMP134 and IGF235 have been found to promote tumor growth and metastasis, while APOL6 has been found to inhibit the migration and invasion of cancer cells." (PMID 38086955, 2023). "The upregulation of APOL6 was correlated with increased response rates and prolonged survival in multiple tumor immunotherapy cohorts." (PMID 36979348, 2023). "Additionally, studies have shown that APOL6 is upregulated in immunotherapy responders, and enhances the efficacy of anti-tumor immunotherapy by promoting tumor cell apoptosis, necrosis, and pyroptosis pathways." (PMID 39308856, 2024). "The function of APOL6 in tumor immunotherapy remains unknown, but was further characterized in this study." (PMID 36979348, 2023). "Bioinformatic analyses suggested that APOL6 may enhance tumor immunotherapy by inducing immunogenic cell death." (PMID 36979348, 2023). "The effect of APOL6 on tumor immunotherapy was evaluated in several immunotherapy cohorts." (PMID 36979348, 2023). "The induction of necroptosis and pyroptosis could augment anti-tumor immune effects, which explains why APOL6 was upregulated in immunotherapy responders." (PMID 36979348, 2023). "Taken together, these results suggest that the upregulation of APOL6 may prolong patient survival by improving the immunotherapy response in multiple tumor types." (PMID 36979348, 2023). "The dose–response relationships of APOL6 and risks of progression/death raised the possibility that increased APOL6 expression in tumor tissues might improve prognosis in patients receiving immunotherapy." (PMID 36979348, 2023). "However, the influence of APOL6 on tumor immunotherapy remains uncharacterized." (PMID 36979348, 2023). "Interestingly, we also identified that Apol6, which induces mitochondria-mediated cell death, was up-regulated in the primary tumor tissues administered with tetraarsenic hexoxide, and its expression was also increased by treatment of tetraarsenic hexoxide in TNBC cells." (PMID 33558527, 2021). "The upregulation of APOL6 improved ICB therapy by inducing immunogenic cell death, thus providing a new therapeutic target for enhancing tumor immunotherapy." (PMID 36979348, 2023). "Early tumor stage, radical resection, low APOL3 expression, high APOL4 and APOL6 expressions, vascular invasion and HBV infection indicated higher survival rates in the TCGA cohort." (PMID 38017264, 2023). "For the TCGA cohort, nomograms were constructed using tumor stage, radical resection, HBV infection, and APOL6 expression for OS." (PMID 38017264, 2023). "ALPL, APOL6, SON, and VWF proteins were significantly differentially expressed between normal and tumor tissues." (PMID 35991564, 2022). "In particular, ALPL, APOL6, SON, and VWF were lowly expressed in tumor tissues." (PMID 35991564, 2022).
cancer (8 papers, 2011 to 2025). A tumor composed of atypical neoplastic, often pleomorphic cells that invade other tissues. "Except for DLBCL, APOL6 expression was weakly associated with TMB or MSI in all other cancers (the absolute values of the correlation coefficients were <0.5)." (PMID 36979348, 2023). "Indeed, APOL6 overexpression has been shown to cause mitochondria-mediated apoptosis in cancer cell lines, and knockdown of APOL6 expression reduced interferon-induced apoptosis in atherosclerotic epithelial cells." (PMID 34252458, 2021). "In addition, APOL6 caused apoptosis when overexpressed in a human cancer cell line." (PMID 34252458, 2021). "APOL6 overexpression leads to apoptosis, which was associated with cytochrome-c and Smac/DIABLO release from the mitochondria of human cancer cells." (PMID 34252458, 2021). "Notably, APOL6, a known tumor suppressor gene, emerged as a potential prognostic biomarker for various cancers." (PMID 40141028, 2025). "The upregulation of APOL6 could improve immunotherapy by triggering immunogenic cell death, thus offering a new target to optimize cancer immunotherapy." (PMID 36979348, 2023). "The novel biomarker APOL6 offers a new approach to optimizing cancer immunotherapy." (PMID 36979348, 2023). "Collectively, the upregulation of APOL6 may enhance ICB therapy by promoting immunogenic cell death in cancers." (PMID 36979348, 2023). "Further studies in larger series of patients are warranted to elucidate this question and determine the specific role of those cancer associated genes (INPP5A, CDX1, MB, CAMK2A, APOL6 vs. VPS53, FAM57A, GEMIN4, SFRS13, ELP2P, GLOD4, CSF2RA and IL3RA), differentially altered in both groups of tumors." (PMID 21811587, 2011). "Besides, APOL6 was identified as one novel BH3-only pro-apoptotic protein and overexpression of APOL6 could induce apoptosis in cancer cells." (PMID 36979348, 2023). "APOL6 induces apoptosis in cancer cells, but apoptotic cells are considered nonimmunogenic." (PMID 36979348, 2023).
infection (4 papers, 2020 to 2025). The state of being infected such as from the introduction of a foreign agent such as serum, vaccine, antigenic substance or organism. "Among these transcripts we identified the apolipoprotein L gene family including, APOL1, APOL2 and APOL6 with up to a fivefold increase of expression (q value ≤ 0.05) after infection with ZIKV." (PMID 39885287, 2025). "ApoL6 protein level was increased by 3-fold upon lentiviral infection and LD size was larger upon h-ApoL6 infection." (PMID 38167864, 2024). "Infection of lentiviral ApoL6 shRNA greatly decreased ApoL6 expression in 3T3-L1 adipocytes." (PMID 38167864, 2024). "In addition, at least three studies have shown expression of APOL1 and APOL6 genes change in response to infection by the intracellular bacterial pathogens Mycobacterium and Listeria." (PMID 34252458, 2021).
kidney disease (1 paper, 2024). "Perspectives regarding the mechanism and treatment of APOL1-related kidney disease are discussed, as well as speculations on additional APOLs functions, such as APOL6 involvement in adipocyte membrane dynamics through interaction with myosin-10 (MYH10)." (PMID 38478101, 2024).
APOL6 also shares sentences with these, for which no sentence is quoted: ZIKV infection (2 papers); bladder cancer (1); breast carcinoma (1); dilated cardiomyopathy (1); glioblastoma (1); Glucose intolerance (1); liver cancer (1); papillary thyroid carcinomas (1); prostate carcinoma (1); rectal adenocarcinoma (1); renal cell carcinoma (1); rheumatoid arthritis (1); spinal cord injury (1); stomach adenocarcinoma (1); urothelial bladder carcinoma (1).